GHSR (growth hormone secretagogue receptor)
Diseases named in the same sentence as GHSR in open-access papers (continued):
Sharing a sentence is not in itself a finding about the gene and the disease.
Hepatic fibrosis (2 papers, 2020 to 2025). The presence of excessive fibrous connective tissue in the liver. "Macrophage GHSR‐Foxo1 axis regulates CCl4‐induced liver fibrosis by promoting inflammation and TGF‐β1‐mediated HSC activation." (PMID 40479577, 2025). "In summary, our study demonstrates the novel role of nutrient‐sensing macrophage GHSR in liver fibrosis, the GHSR−Foxo1 nexus is an important regulatory pathway in liver macrophages to inflammation and fibrosis." (PMID 40479577, 2025). "This study uses a carbon tetrachloride (CCl4)‐induced liver fibrosis mouse model to investigate the role of macrophage GHSR in liver fibrosis." (PMID 40479577, 2025). "To elucidate the effect of CCl4 on liver fibrosis and GHSR expression, we administered CCl4 to wild‐type (WT) mice and found that CCl4 reduced body weight but increased liver‐to‐body weight ratio." (PMID 40479577, 2025). "Our findings suggest that suppressing GHSR signaling in macrophages may serve as a novel therapeutic strategy for liver fibrosis." (PMID 40479577, 2025). "GHSR, as a GPCR, is a favorable drug target, that may serve as a novel immunotherapeutic strategy for the treatment of liver fibrosis." (PMID 40479577, 2025).
oral cancer (2 papers, 2019 to 2021). "According to the grayscale statistical analysis of scanning image software, the positive indices of ghrelin and GHSR gradually increased from normal epithelium-to-mild, -moderate, and -severe dysplasia, then culminating in oral cancer." (PMID 31750884, 2019). "The GHSR positive index gradually increased from 0.524166667 in normal epithelium to 2.947433333 in mild dysplasia, 8.678533333 in moderate dysplasia, 24.84486667 in severe dysplasia, and 30.58046667 in oral cancer." (PMID 31750884, 2019). "With the aggravation of the degree of epithelial dysplasia, that is, the sequence changes from normal to light, medium and severe dysplasia and oral cancer, the expression of GHSR gradually increased and was positively correlated with Ghrelin, and the positive staining area gradually expanded." (PMID 31750884, 2019). "In normal keratinocytes (HOK), oral abnormally proliferating cells (LEUK1), oral cancer cells (CAL27), and sequence malignant cell lines, ghrelin, GHSR, mTOR, and phospho-mTOR showed the same increasing trend and correlation." (PMID 31750884, 2019).
osteoporosis (2 papers, 2015 to 2017). A condition of reduced bone mass, with decreased cortical thickness and a decrease in the number and size of the trabeculae of cancellous bone (but normal chemical composition), resulting in increased fracture incidence. "Additionally, osteoporosis in humans using growth hormone secretagogue receptor (GHSR) agonists has had minor success in post-menopausal women." (PMID 28704966, 2017).
status epilepticus (2 papers, 2013 to 2017). Status epilepticus is defined as a continuous seizure lasting more than 30 min, or two or more seizures without full recovery of consciousness between any of them. "In models of status epilepticus ghrelin displays neuroprotective effects mediated by the growth hormone secretagogue-receptor 1a (GHS-R1a)." (PMID 24015271, 2013).
thymoma (2 papers, 2021 to 2022). A neoplasm arising from the epithelial cells of the thymus. "Growth hormone secretagogue receptor (GHSR) hypermethylation was observed in thymoma samples of MG patients, especially in late stages of disease." (PMID 34603387, 2021). "In a subsequent study, the same study group speculated that DNA methylation of GHSR correlates with a shift from native to variant expression, thus inducing the tumorigenesis of thymoma, yet not TC." (PMID 35409405, 2022). "Bisulfite pyrosequencing in 46 TEN and 20 paired thymus tissues revealed higher promoter methylation of G protein subunit gamma 4 (GNG4), growth hormone secretagogue receptor (GHSR), homeobox D9 (HOXD9) and spalt like transcription factor 3 (SALL3) in TC than in thymoma." (PMID 35409405, 2022).
cervical intraepithelial neoplasia (1 paper, 2021). "Significantly elevated levels were observed for GHSR and LHX8 in relation to high-grade cervical intraepithelial neoplasia (CIN2 +; n = 33), with area under de curve values of 0.80 (95% Confidence Interval (CI) 0.59–0.92) and 0.76 (95% CI 0.58–0.89), respectively." (PMID 33846517, 2021).
dilated cardiomyopathy (1 paper, 2025). Cardiomyopathy which is characterized by dilation and contractile dysfunction of the left and right ventricles. "We sought to determine alterations in myocardial GHSR together with markers of cardiac inflammation using mdx:utrn−/− mice as a model for DMD-associated dilated cardiomyopathy." (PMID 40643523, 2025). "Imaging GHSR in mdx:utrn−/− mice represents a step towards the detection of early biomarkers for inflammation and dilated cardiomyopathy." (PMID 40643523, 2025). "Therefore, we reasoned that the expression and distribution of GHSR would also be altered during the progression of dilated cardiomyopathy in DMD mice." (PMID 40643523, 2025).
Follicular Cyst (1 paper, 2023). Cyst due to the occlusion of the duct of a follicle or small gland. "Our data also showed that the mRNA expressions of ESR1, ESR2, PGR, IGF1Rs and GHSR were changed in follicular cysts." (PMID 37958056, 2023).
gastric adenocarcinoma (1 paper, 2024). "GHRL (Ghrelin) is a hormone that is highly expressed in gastric adenocarcinoma and is involved in tumour development by binding to its receptor, GHSR." (PMID 38752750, 2024).
Gastrointestinal obstruction (1 paper, 2023). "These include ulimorelin, an agonist of the ghrelin hormone secretagogue receptor GHSR used to treat gastrointestinal obstruction." (PMID 36823319, 2023).
glucose metabolic disorders (1 paper, 2018). "Therefore, deletion of GHSR could improve the glucose metabolic disorders induced by high fat diet." (PMID 30112394, 2018).
immunotoxicity (1 paper, 2023). "Our study unveiled an important functional relationship between BPA immunotoxicity and ghrelin receptor GHSR function in macrophages." (PMID 37510359, 2023). "Further understanding how nutrient-sensing GHSR signaling regulates BPA intestinal immunotoxicity will help design new strategies to mitigate BPA immunotoxicity and provide policy guidance for BPA biosafety." (PMID 37510359, 2023). "Furthermore, we generated Ghsr deletion mutants and conducted functional assays and confirmed that GHSR is required for BPA-induced immunotoxicity in macrophages." (PMID 37510359, 2023). "However, it is unknown whether the macrophage GHSR signaling is involved in the modulation of BPA immunotoxicity." (PMID 37510359, 2023).
infiltrating ductal breast carcinomas (1 paper, 2007). "Strikingly, the approach identified a single locus within the promoter region of the GHSR gene that is hypermethylated in 90% (92 of 102) of infiltrating ductal breast carcinomas, independently of patient age or tumor stage." (PMID 18091988, 2007).
ischemic cardiomyopathy (1 paper, 2020). Ischemic cardiomyopathy is a cardiomyopathy in which a weakness in the muscle of the heart due to inadequate oxygen delivery to the myocardium with coronary artery disease being the most common cause. "The potential for ligands based on the GHRP-6 structure to target ischemic cardiomyopathy was however limited due to their lack of receptor selectivity, binding to both CD36 and the growth hormone secretagogue receptor (so-called ghrelin receptor, GHS-R1a)." (PMID 32717955, 2020).
liver inflammation (1 paper, 2025). "Taken together, these findings suggest that macrophage GHSR may be involved in controlling CCl4‐induced liver inflammation and fibrosis." (PMID 40479577, 2025). "Macrophage GHSR controls inflammation and TGF‐β1 expression via protein kinase A (PKA)‐mediated Forkhead box protein O 1 (Foxo1) phosphorylation at S273; Foxo1‐S273D mutation, mimicking constitutive phosphorylation of Foxo1 at S273, shows exacerbated CCl4‐induced liver inflammation and fibrosis." (PMID 40479577, 2025).
oropharyngeal carcinoma (1 paper, 2020). Carcinoma, predominantly squamous cell, arising from the epithelial cells of the oropharynx. "Furthermore, in HPV-related oropharyngeal cancer (n = 37), GHSR and NMUR1 hypermethylation was significantly associated with shorter DFS (log-rank test, P = 0.003 and P = 0.026, respectively)." (PMID 31974445, 2020). "For correlation analysis of the association between tumor HPV status, GHSR methylation status, and NMUR1 methylation status with survival, we combined data for all patients with oropharyngeal carcinoma." (PMID 31974445, 2020). "In the current study, we presented the relationship between the methylation status of the GHSR and NMUR1 genes and recurrence in HNSCC, specifically in risk classification of oropharyngeal carcinomas cases with HPV status." (PMID 31974445, 2020). "In patients with oropharyngeal cancer (n = 75), GHSR and NMUR1 promoter methylation significantly correlates with survival in surgically treated patients." (PMID 31974445, 2020). "Notably, the OR was significantly higher in HPV-positive oropharyngeal cancer patients (n = 37) in whom the GHSR promoter was methylated (OR, 19.00; 95% CI, 1.87–193.01; P = 0.013)." (PMID 31974445, 2020). "In addition, the site-specific analysis revealed that abnormal CpG island hypermethylation in the GHSR and NMUR1 promoters was independently associated with aggressive clinical behavior in oropharyngeal cancer." (PMID 31974445, 2020). "Our results indicate that the methylation status of the GHSR and NMUR1 genes is an independent prognostic indicator for patients with oropharyngeal cancers." (PMID 31974445, 2020). "It is worth noting that the GHSR and NMUR1 methylation status is a strong predictor of poorer survival among patients with HPV-positive oropharyngeal cancer." (PMID 31974445, 2020). "Methylation of the GHSR and NMUR1 promoters correlated positively with recurrence in oropharyngeal cancer patients, both individually (OR, 3.853; 95% CI, 1.510–9.832; P = 0.005 and OR, 2.872; 95% CI, 1.172–7.037; P = 0.036, respectively) and together (OR, 3.272; 95% CI, 1.216–8.801; P = 0.019)." (PMID 31974445, 2020).
pharyngeal cancers (1 paper, 2020). "Loss of GHSR expression correlates with hypermethylation of GHSR in breast, cervical, prostate, pancreatic, colorectal, and pharyngeal cancers, and glioblastoma." (PMID 31974445, 2020).
thyroid carcinoma (1 paper, 2017). "Ghrelin and GHSR were expressed in human thyroid carcinoma cells." (PMID 28977162, 2017).
cancer (58 papers, 2012 to 2026). A tumor composed of atypical neoplastic, often pleomorphic cells that invade other tissues. "HPV-positive cancer patients were regarded to be at low-risk, with the exception of patients with both GHSR and NMUR1 methylated." (PMID 31974445, 2020). "Ghrelin and/or GHSR has been implicated in the maintenance as well as progression of several human malignant tumors, including esophageal 15, gastric 16, lung 17, and endometrial cancer." (PMID 27464938, 2016). "A number of studies have linked single nucleotide polymorphisms (SNPs) in the ghrelin (GHRL) or ghrelin receptor (GHSR) genes with cancer risk." (PMID 25376984, 2014). "Further studies with larger and more well-defined sample populations are warranted to verify the role of GHRL and GHSR polymorphisms in cancer." (PMID 25376984, 2014). "Here, we perform a meta-analysis of case–control studies that have correlated ghrelin and GHSR gene polymorphisms with cancer risk to elucidate further the association between ghrelin axis gene polymorphisms and cancer." (PMID 25376984, 2014). "Since the first publication reporting the antiproliferative effect of ghrelin, numerous cancer studies suggested a role for the ghrelin/GHSR system in various tumours, modulating proliferation, apoptosis, and metastasis." (PMID 38137497, 2023). "In bladder cancer tissue, GHSR-1a is also highly expressed, and ghrelin induces immunosuppressive T regulatory cells, which would promote cancer cell proliferation." (PMID 35454071, 2022). "This important finding will facilitate the future comprehensive analysis and research of the ghrelin–GHSR signaling pathway and its downstream cascade in the development and spread of various cancers." (PMID 36235843, 2022). "Anamorelin is developed as a small molecule to enhance protein synthesis by binding the ghrelin/growth hormone secretagogue receptor (GHSR), aiming at the treatment of malignant cachexia." (PMID 32570738, 2020). "IHC in vivo experiments confirmed that ghrelin and GHSR positive indices in severe dysplasia and cancer stage had very significant differences with normal cells, and mild and moderate dysplasia, respectively." (PMID 31750884, 2019). "3-Hydroxyoxindole scaffolds are prevalent in natural products and biologically relevant molecules, and have exhibited diverse biological activities such as inhibition of proteasome, antagonizing GHSR and inhibiting growth of human cancer cells." (PMID 27340490, 2016). "The ghrelin/des-acyl ghrelin–cancer axis is complex, one reason being that tumor cells have been shown to express splice variants of ghrelin, and ghrelin and des-acyl ghrelin might act at receptors other than the cognate ghrelin receptor, growth hormone secretagogue receptor 1a, in tumors." (PMID 28119851, 2016). "Variations in the amount of GHSR expression may contribute to the disparities in cell proliferation and resistance to apoptosis between cancer and normal cells." (PMID 38137497, 2023). "It is worth noting that the observed inhibitory Ser366 phosphorylation of eEF2K may limit cancer cell migration and metastasis, although an increased metastatic growth has been reported for a number of cancer types with the active ghrelin-GHSR axis." (PMID 35841486, 2022). "In addition, different compounds have been tested for cancer cachexia atrophy, among which: androgen receptor modulators, bimagrumab, ghrelin, and growth hormone secretagogue receptor synthetic agonists." (PMID 36010642, 2022). "In this review, we focus primarily on the potential of In1-ghrelin as a biomarker for cancer progression, the unique characteristics of UAG and AG, the importance of the two known receptor variants GHSR-1a and 1b, as well as the possible mechanisms through which the ghrelin axis acts." (PMID 35454071, 2022). "Likewise, a clinical study on patients with pancreatic neuroendocrine tumors reported local co-expression of ghrelin and GHSR in cancer tissue resulted in worse survival." (PMID 31681567, 2019).
cancer (continued). "The ANOVA results showed that ghrelin and GHSR positive indices in severe dysplasia and cancer with normal, mild and moderate dysplasia were significantly different (P < 0.01), and the ghrelin positive index in the severe dysplasia and cancer data were also significantly different (P < 0.05)." (PMID 31750884, 2019). "NTSR1, NTSR2, GHSR, MLNR, and NMUR1 promoter hypermethylation presented discriminative ROC curve profiles, which clearly differentiate cancer tissues from normal tissues [Area Under Curve (AUC) = 0.6220, 0.5736, 0.8103, 0.6049, and 0.5631, respectively]." (PMID 31974445, 2020). "It is well-documented that ghrelin and its receptor, the growth hormone secretagogue receptor (GHSR), are expressed in a broad array of normal tissues and cancer types, and they are considered to function as autocrine/paracrine growth factors." (PMID 28977162, 2017). "There is growing evidence that the ghrelin axis, including ghrelin (GHRL) and its receptor, the growth hormone secretagogue receptor (GHSR), play a role in cancer progression." (PMID 25376984, 2014). "Together, these data suggest that GHSR-1a and -1b may have distinctive functions in cancer progression, and GHSR-1b may serve as potential clinical biomarker in cancers." (PMID 35454071, 2022). "Of these seven, six genes—ECT2, NCEH1, TNFSF10, FNDC3B, GHSR, and SEMA6D—have either been observed at elevated expressions in tumor cells or have been documented acting as oncogenes for specific cancers in humans (genes that can transform cells into tumor cells)." (PMID 33767816, 2021). "Actually, atractylodin is of great clinical potential, because GHSR is expressed in the gastrointestinal tract, hypothalamic NYP/AgRP nerve, human monocytes and T cells, pancreatic, lymphoid, and reproductive tissues, and even some cancer cell lines." (PMID 28883883, 2017).